DEK (DEK proto-oncogene)
Diseases named in the same sentence as DEK in open-access papers (continued):
Sharing a sentence is not in itself a finding about the gene and the disease.
bladder cancer (9 papers, 2005 to 2023). "Several reports indicate that DEK is associated with bladder tumor tissue, which includes mRNA overexpression studies by microarray and amplification of 6p22.3 region of chromosome, wherein the DEK gene is located, in 25% of advanced stage bladder cancer." (PMID 21663673, 2011). "Based on these studies, one would predict that DEK protein might be associated with the development of bladder cancer." (PMID 21663673, 2011). "The oncogene DEK is overexpressed in several malignancies including melanoma, hepatocellular carcinoma, glioblastoma, retinoblastoma, and bladder cancer." (PMID 21663673, 2011). "Here we show that oncoprotein DEK can be used as a biomarker for detection of bladder cancer using patient urine samples." (PMID 21663673, 2011). "Based on our study, the presence of DEK protein is largely specific for bladder cancer with a few cases wherein DEK protein is present in renal and prostate cancer." (PMID 21663673, 2011). "A region of genomic gain on chromosome 6p22 that has been detected in high grade bladder cancer tumors contains the DEK gene." (PMID 21663673, 2011). "To test if bladder cancer cells also secrete DEK protein, we analyzed conditioned media obtained from bladder cancer cell line 5637." (PMID 21663673, 2011). "The presence of DEK protein in voided urine is potentially a suitable biomarker for bladder cancer and that the screening for the presence of DEK protein in urine can be explored as a noninvasive diagnostic test for bladder cancer." (PMID 21663673, 2011). "We are the first to show that DEK protein can be detected in the urine of bladder cancer patients by western blot analysis using a commercially available polyclonal DEK antibody." (PMID 21663673, 2011). "Results from western blot analysis indicate that DEK is expressed in all bladder cancer cell lines as well as in normal bladder epithelial cell line UroTSA." (PMID 21663673, 2011). "For the same bladder cancer tissue panel, we also studied the protein expression of these two diagnostic markers, survivin and DEK, using Western blot assay (data not shown)." (PMID 23342256, 2012). "Next, we determined if the DEK protein is present in urine of bladder cancer patients." (PMID 21663673, 2011). "We are the first to show that the DEK protein is present in the urine of bladder cancer patients." (PMID 21663673, 2011). "Furthermore, the presence of DEK protein in the urine of bladder cancer patients, makes the detection of DEK protein in the urine of patients as an attractive diagnostic for bladder cancer." (PMID 21663673, 2011). "We are encouraged to further analyze DEK as a biomarker of bladder cancer using larger number of patient samples that will allow us to further strengthen the presence of DEK protein in the urine of bladder cancer patients as a biomarker for bladder cancer." (PMID 21663673, 2011). "Results show that DEK protein is detected in 16 out of 19 urine samples of bladder cancer patients." (PMID 21663673, 2011). "Furthermore, using bladder tumor cDNA microarrays, DEK mRNA was significantly up regulated in bladder cancer." (PMID 21663673, 2011). "The DEK protein is present in the voided urine of patients with low and high grade bladder cancer." (PMID 21663673, 2011). "This study is limited to detection of DEK protein in the urine of diagnosed TCC patients with first incidence or recurrence of bladder cancer and not in high risk individuals." (PMID 21663673, 2011). "Indeed, DEK protein was present in the voided urine of patients with low- and high-grade bladder cancers, suggesting that DEK could be used as a biomarker for detection of bladder cancer using patient urine samples." (PMID 25340858, 2014). "Indeed, DEK protein was shown to be present in the voided urine of patients with both low- and high-grade bladder cancer, suggesting that DEK could be used as a biomarker for detection of this cancer using patient urine samples." (PMID 23902796, 2013).
bladder cancer (continued). "Furthermore, the DEK protein is present in the voided urine of patients with bladder cancer." (PMID 21663673, 2011). "To test if high levels of DEK protein are present in bladder cancer cell lines, we prepared whole cell lysates using RIPA buffer from bladder cancer cell lines RT-4, 5637, T-24 and TCCPSUP derived from increasing grades of bladder cancer." (PMID 21663673, 2011). "In the present study, we have therefore investigated to which extent ID4 gene copy numbers and expression are affected by 6p22 amplifications in bladder cancer, in comparison to E2F3 and DEK." (PMID 15876350, 2005). "We found that both survivin and DEK are present and overexpressed in over 80% of bladder cancer tissues regardless of clinical and pathological stage, which is consistent with previous literature report." (PMID 23342256, 2012). "Given its numerous functions in cancer cells, it is no surprise that DEK expression could be used as a biomarker for colorectal and bladder cancers and possibly other solid tumors as well." (PMID 26425120, 2015). "However, there is no published literature to support increased DEK protein levels in bladder tumors and in the urine of bladder cancer patients." (PMID 21663673, 2011). "Based on our pilot study of 38 bladder tumor tissue and 42 urine samples from patients with active TCC, other malignant urogenital disease, non-malignant urogenital disease and healthy individuals; DEK protein is expressed in bladder tumor tissue and voided urine of bladder cancer patients." (PMID 21663673, 2011). "Results show that DEK is absent in the conditioned media of bladder cancer cell line 5637 indicating that DEK may not be secreted by bladder cancer cells." (PMID 21663673, 2011).
hepatocellular carcinoma (9 papers, 2013 to 2023). A malignant tumor that arises from hepatocytes. "Interestingly, macrophages are not the only cells to secrete DEK; conditioned media from HepG2 hepatocellular carcinoma cells were also found to contain DEK peptides." (PMID 26425120, 2015).
retinoblastoma (9 papers, 2007 to 2024). A malignant tumor that originates in the nuclear layer of the retina. "Transcriptome profiles revealed gradual development of a retinoblastoma expression signature in RB1ko with upregulation of proliferation-associated genes and retinoblastoma-related oncogenes such as DEK, SYK and HELLS." (PMID 35565295, 2022). "Plotting the expression of genes known to be associated with retinoblastoma development, such as MDM2, DEK, SYK and HELLS, confirmed their upregulation in RB1ko when compared to RB1wt and RB1het and in the tumor specimens." (PMID 35565295, 2022). "DEK is localized in chromosome 6p, the region frequently observed to be amplified in retinoblastoma, which also encompasses another oncogene (E2F3)." (PMID 29914080, 2018). "We can envisage a similar role of regulating apoptosis by DEK in retinoblastoma." (PMID 29914080, 2018). "Besides, we identified DEK protein to be hyperphosphorylated in retinoblastoma." (PMID 29914080, 2018). "Transcriptome analysis of RB1 knockout organoids and primary retinoblastoma revealed gain of a retinoblastoma expression signature in the organoids, characterized by upregulation of RBL1 (p107), MDM2, DEK, SYK and HELLS." (PMID 35565295, 2022). "We did observe subtle elevation in the expression of DEK, NUP153, E2F3 and TTRAP and additional studies will be required to determine the functional significance of elevated gene expression in human retinoblastoma." (PMID 24509483, 2014). "Both DEK and E2F3 have been identified as over-expressed transcripts due to chromosome 6p gains in retinoblastoma, a common pediatric malignancy." (PMID 17397536, 2007).
squamous cell carcinoma (9 papers, 2015 to 2025). A carcinoma arising from squamous epithelial cells. "DEK has been reported to play important roles in the progression of early and late stage squamous cell carcinoma (SCC) and is useful for early diagnosis of the disease." (PMID 32656741, 2020). "Our reported in vitro and in vivo models of squamous cell carcinoma have demonstrated that DEK contributes functionally to cellular and tumor survival and to proliferation." (PMID 28558019, 2017). "These include, among others, the identification of a subset of sinonasal carcinomas associated with HPV infection, the identification of a subset of squamous cell carcinomas with EGFR alterations, and of rare variants with chromosomal translocations (DEK::AFF2, ETV6::NTRK and others)." (PMID 35326613, 2022). "Previous studies have demonstrated that over-expressing DEK in human immortalized keratinocytes and squamous cell carcinomas results in a significant increase in lactate production and subsequent accumulation in conditioned media as a result of metabolic reprogramming." (PMID 32708944, 2020). "Although some transcriptional DEK targets have been described, the DEK-dependent transcriptome in squamous cell carcinomas remains unknown." (PMID 26527316, 2015). "DEK::AFF2 fusion squamous cell carcinoma (SCC) is a rare and aggressive subtype of non-keratinizing SCC." (PMID 40299135, 2025).
lymph node metastasis (8 papers, 2013 to 2023). "Here we have demonstrated that high DEK expression is associated with serosal invasion, lymph node metastasis, tumor size and differentiation, which are crucial histological features associated with poor prognosis in colorectal cancer." (PMID 23902796, 2013). "High expression of DEK in pancreatic cancer has been found to promote lymph node metastasis and to be related to poor prognosis." (PMID 35698073, 2022). "DEK overexpression in CRCs was positively correlated with tumor size, grade, lymph node metastasis, serosal invasion, late stage, and disease-free survival and 5-year survival rates." (PMID 25340858, 2014). "DEK expression was more commonly seen in cases presenting with poor prognostic factors of colorectal cancer, leading to lymph node metastasis, late-stage, serosal invasion and reduced survival time." (PMID 23902796, 2013). "In our present study we first determined that DEK expression was markedly higher in TNBC tissues and cells, and correlated with clinical stage, differentiation, and lymph node metastasis." (PMID 29228721, 2017). "Similarly, colorectal cancer with lymph node metastasis and high DEK expression, had a significantly lower 5-year survival rate than colorectal cancer with lymph node metastasis in the absence of DEK expression (P=0.001)." (PMID 23902796, 2013). "Similarly, we found that the strongly positive rate of DEK protein was significantly higher in colorectal cancers with lymph node metastasis (63.27%, 31/49) than in cases without metastasis (36.67%, 22/60) (P=0.006)." (PMID 23902796, 2013).
prostate carcinoma (8 papers, 2011 to 2022). A carcinoma that arises from epithelial cells of the prostate gland. "Elevated DEK expression was found to be an independent clinical risk factor, associated with shorter disease-free survival of hormonal naïve prostate cancer patients." (PMID 25544761, 2015). "To validate the association of DEK expression with NEPC, we examined DEK mRNA expression in a panel of patient tissue-derived prostate cancer xenograft models." (PMID 25544761, 2015). "Therefore, we investigated whether increased DEK expression may provide a novel prognostic marker to aid risk stratification of hormonal naïve prostate cancers." (PMID 25544761, 2015). "Among them, DEK stabilization contributes to prostate cancer invasion and stem cell-like property and DEK upregulation correlates with SPOP mutations, in prostate cancer." (PMID 27200299, 2016). "The results suggest that DEK plays an important role in the progression of prostate cancer, especially to NEPC, and provides a potential biomarker to aid risk stratification of prostate cancer and a novel target for therapy of NEPC." (PMID 25544761, 2015). "It's suggested that increased expression of DEK is an independent prognostic factor in prostate cancer." (PMID 25544761, 2015). "In conclusion, the findings of the present study suggest that DEK plays an important role in the progression of prostate cancer, especially to NEPC." (PMID 25544761, 2015). "Further study on DEK regulated genes/pathways will provide insights to the mechanism of DEK regulated NE differentiation of prostate cancer." (PMID 25544761, 2015). "In this study, we demonstrated that increased DEK expression is an independent prognostic factor in prostate cancer." (PMID 25544761, 2015). "The expression of DEK protein was examined using IHC in independent clinical prostate cancer tissue microarrays (TMAs) containing 69 benign prostate, 163 adenocarcinoma, 44 CRPC and 6 NEPC cases." (PMID 25544761, 2015). "To study functional roles of DEK in prostate cancer, we examined effects of decreased DEK expression on PC-3 cells, a cell line characteristic of prostatic small cell neuroendocrine carcinoma." (PMID 25544761, 2015). "To gain more detailed insights into the function of the DEK gene in NEPC development, we performed microarray gene expression analysis on control-treated and DEK silenced PC-3 prostate cancer cells." (PMID 25544761, 2015). "Elevated DEK protein expression may serve as a novel prognostic factor for prostate cancer patients." (PMID 25544761, 2015). "This study showed that in LHMAR and LNCaP cell lines, SPOP mutant-related or vector-based overexpression of DEK significantly promotes cell invasion and knockdown of DEK decreases cell invasion of cells overexpressing mutant SPOP, which implicates DEK as an oncogenic effector in prostate cancer." (PMID 25544761, 2015). "This study provides further independent evidence for the functional role of DEK in prostate cancer." (PMID 25544761, 2015). "In the present study, elevated DEK protein expression was observed in all NEPC xenograft models and clinical NEPC cases, as opposed to their benign counterparts (0%), hormonal naïve prostate cancer (2.45%) and castration-resistant prostate cancer (29.55%)." (PMID 25544761, 2015). "Recently, DEK was identified as an SPOP substrate that exhibited decreases in ubiquitylation and proteasomal degradation and increase in expression in SPOP-mutant prostate cancer." (PMID 25544761, 2015).
autoimmune disease (7 papers, 2007 to 2024). A disorder resulting from loss of function or tissue destruction of an organ or multiple organs, arising from humoral or cellular immune responses of the individual to their own tissue constituents. "While DEK has been implicated in immune responses previously, particularly as an auto-antigen in autoimmune diseases and as a major component of neutrophil extracellular traps (NETs), its role in directing the tumor-immune response and the tumor microenvironment has never before been investigated." (PMID 32708944, 2020). "The majority of previous reports have focused on the role of DEK in solid tumors and hematologic malignancies, autoimmune diseases, and hematopoiesis." (PMID 33304240, 2020). "DEK is an abundant, highly conserved phosphoprotein with documented roles in autoimmune diseases and solid tumor progression." (PMID 32708944, 2020). "DEK autoantibodies have been found in the serum and synovial fluid of patients with many different autoimmune disorders including juvenile idiopathic arthritis (JIA), systemic lupus erythematosus (SLE), sarcoidosis, and rheumatoid arthritis." (PMID 26425120, 2015). "Specifically, we address the role of DEK in chronic inflammation via viral infections and autoimmune diseases, the overexpression and oncogenic activity of DEK in cancers, and DEK-mediated regulation of NFκB signaling." (PMID 26425120, 2015). "DEK is a nuclear protein, and antibody responses to DEK have been proposed to be indicators of autoimmune disease." (PMID 17397536, 2007). "DEK is overexpressed in a majority of solid tumors, and is also known to be an autoantigen in autoimmune disorders such as juvenile idiopathic arthritis." (PMID 33304240, 2020). "In addition to anti-DEK autoantibodies, which are produced by B cells, T cells may also become falsely activated in autoimmune diseases through the presentation of DEK peptides by HLA-A molecules." (PMID 26425120, 2015). "DEK (OMIM #125,264) is a chromatin-remodeling gene that is expressed in most human tissues and is well known for its role in cancer biology and in autoimmune diseases." (PMID 34303382, 2021).
juvenile idiopathic arthritis (6 papers, 2011 to 2025). Juvenile idiopathic arthritis (JIA) is the term used to describe a group of inflammatory articular disorders of unknown cause that begin before the age of 16 and last over 6 weeks. "In juvenile arthritis patients, DEK is found in the neutrophil extracellular traps (NETs) of the synovial fluid, and targeting DEK can reduce the formation of NETs and joint inflammation." (PMID 33124760, 2020). "Notably, DEK, a nuclear chromatin protein, acts as a chemical attractor inducing juvenile idiopathic arthritis." (PMID 39668431, 2025). "Interestingly, anti-DEK autoantibodies have been identified in juvenile rheumatoid arthritis and other inflammatory diseases." (PMID 38255677, 2023). "DEK is a secreted protein abundant in the synovia of patients with juvenile idiopathic arthritis." (PMID 28165452, 2017). "Furthermore, autoantibodies to DEK have been detected in juvenile rheumatoid arthritis, systemic lupus erythematosus and sarcoidosis." (PMID 21663673, 2011). "The nuclear chromatin protein DEK is a secreted chemoattractant that is abundant in the synovia of patients with juvenile idiopathic arthritis (JIA)." (PMID 28165452, 2017). "Previous studies have demonstrated that patients with Juvenile Rheumatoid Arthritis (JRA), have auto-antibodies against DEK protein and DEK protein is found to be secreted in the synovial fluid of JRA patients." (PMID 21663673, 2011).
Alzheimer disease (5 papers, 2020 to 2025). A progressive, neurodegenerative disease characterized by loss of function and death of nerve cells in several areas of the brain leading to loss of cognitive function such as memory and language. "Reducing DEK levels in these neurons in vitro leads to changes reminiscent of early Alzheimer’s disease pathology." (PMID 38462574, 2024). "The role of DEK and AKT in cellular survival suggests their functional mechanisms in Alzheimer’s disease." (PMID 32736520, 2020).
Arthritis (5 papers, 2015 to 2025). Inflammation of a joint. "Additionally, multiallelic marker genotyping and SNP genotyping revealed that the 3′ UTR of DEK was associated with rheumatoid arthritis susceptibility, further supporting evidence that DEK may be a crucial component of arthritis related chronic inflammation." (PMID 26425120, 2015). "DEK is also important for the development of arthritis in mouse models, and the elimination or depletion of DEK can effectively relieve arthritis." (PMID 39668431, 2025). "Here, we show that DEK is crucial to the development of arthritis in mouse models, thus making it an appropriate target for aptamer-based therapy." (PMID 28165452, 2017). "We demonstrate here that genetic depletion and aptamer-mediated targeting of DEK confers protection against arthritis in a murine model of inflammatory arthritis." (PMID 28165452, 2017). "DEK appears to be a key player in arthritis, and anti‐DEK reagents may be used for the treatment of JIA and other types of arthritis." (PMID 40060194, 2025). "Here the authors show DEK is important for neutrophil extracellular trap formation and joint inflammation, and demonstrate therapeutic efficacy of DEK-targeting aptamers in a mouse model of arthritis." (PMID 28165452, 2017). "As DEK-targeting aptamers reduce NET formation in zymosan-injected joints and human peripheral blood neutrophils, we conclude that targeting DEK in the setting of arthritis, especially with aptamers, may serve as a viable therapeutic strategy." (PMID 28165452, 2017).